TNF (tumor necrosis factor)
Diseases named in the same sentence as TNF in open-access papers (continued):
Sharing a sentence is not in itself a finding about the gene and the disease.
tumor (continued). "The virus infiltration causes inflammation and lymphocyte penetration into the tumor, and the virus protein leads to increased sensitivity to tumor necrosis factor-mediated killing." (PMID 23533319, 2013). "More knowledge should be gained on tumor risk after infliximab therapy in patients with previous malignancies, possibly discouraging use of TNF-α-inhibitors in future cases." (PMID 23762724, 2013). "In particular, they observed that EPA inhibited the TNF-α-induced expression of a matrix metalloproteinase (MMP-9) specifically associated to tumor cell invasion and metastases in HaCaT keratinocytes." (PMID 23691510, 2013). "TNF and TGFβ were selected because within the tumor microenvironment, TNF is believed to be produced predominantly by tumor-associated macrophages, while TGFβ is secreted by fibroblast and endothelial cells." (PMID 23935876, 2013). "TNF is produced in the tumor microenvironment mainly by macrophages, but also by smooth muscle cells, ECs and tumor cells, and it affects primarily the tumor-associated vasculature." (PMID 24062984, 2013). "Taken together, these observations suggest that TNFα is recruited downstream of other tumor-associated mediators." (PMID 24067145, 2013). "TNF-α is implicated in the processes of tumor growth, survival, differentiation, invasion, metastases, secretion of cytokines, and proangiogenic factors." (PMID 23573150, 2013). "Although TNFα was initially associated with tumour necrosis, mounting evidence suggests that TNFα plays a role in tumour growth and progression, induction of genes involved in inflammation, tissue repair and angiogenesis." (PMID 24083678, 2013). "Tumor necrosis factor alpha (TNF-α) is a pleiotropic cytokine that exerts its antitumor effects mainly through a combination of preferential toxicity for tumor-associated endothelial cells and through an increase in the antitumor immune response." (PMID 24156020, 2013). "TNF-α is an essential factor in tumor promotion, and IL-1 polymorphisms are important mediators in the inflammatory process." (PMID 24959547, 2013). "In a mouse model of metastatic melanoma, TNF-α caused enhanced tumor progression through the TNFR2-mediated Treg expansion at the site of metastasis." (PMID 23986759, 2013). "In CLL, bidirectional GITR/GITRL signaling can support tumor cell growth by causing release of survival factors, such as IL-6, IL-8, and TNF, and interfering with rituximab-induced ADCC responses." (PMID 24391651, 2013). "TNF-α promotes cancer cell apoptosis and tumor-associated killing through the tumor necrosis factor-related apoptosis-inducing ligand (TRAIL) signaling pathway." (PMID 24278120, 2013). "Loss of FXR increased tumor progression via promoting Wnt signaling by infiltrating neutrophils and macrophages, and elevated the tumor necrosis factor α (TNFα) production in vivo." (PMID 23341777, 2013). "Although the role of TNF-α in tumor development is not fully understood, an increased risk of malignancy with TNF-α-inhibitors, such as infliximab, has been suggested." (PMID 23762724, 2013). "During cancer progression, secretion of TGFβ within the tumor microenvironment occurs through many different cell types, including tumor-associated fibroblasts, while secretion of TNF originates from tumor-associated M2 macrophages." (PMID 23935876, 2013). "TNF-α was identified and isolated because of antiangiogenic activity; when injected into tumors, it causes tumor vessels to regress resulting in tumor necrosis." (PMID 23365490, 2013). "We have, however, recently demonstrated TNF-mediated induction of TNFR2 in tumor stem cells in ccRCC organ cultures in association with increased cell cycle entry (RSL; unpublished observations)." (PMID 24350291, 2013). "The production of inflammatory cytokines such as TNF-α and IL-1 by tumor-associated macrophages can act as potent stimulator of metastasis." (PMID 23691510, 2013).
tumor (continued). "MCP-1 or MIP-1 loss significantly promotes primary tumor growth and lung metastasis by inhibiting IL-6, TNF-α and TGF-β expression." (PMID 23426399, 2013). "The serum TNF-α level was evaluated with enzyme-linked immunosorbent assay (ELISA) once a week for up to 6 weeks post tumor inoculation." (PMID 22808019, 2012). "The reduction of tumor growth was associated with higher TNF-α and granzyme B production, which are both known to induce programmed cell death." (PMID 23028986, 2012). "They showed that antigen-specific T cells can kill antigen-loss variants in an IFN-γ- and TNF-α-dependent manner and can cure mice with an even larger tumor burden." (PMID 22479645, 2012). "IL-6 and TNF-α are the major pro-inflammatory cytokines implicated in inflammation-associated carcinogenesis, enhancing tumour cell growth." (PMID 23176085, 2012). "We utilized an experimental model of TNF-α-mediated inflammation to characterize inflammatory gene expression in tumor-associated endothelial cells." (PMID 23056240, 2012). "Deleting both Cys25 and Cys27 would result in monomers and loss of Tipα’s bioactivities in NF-κB activation, TNF-α induction, and tumor promotion." (PMID 22860022, 2012). "Constitutive production of TNF from the tumor microenvironment is a characteristic of many malignant tumors, and the presence of TNF is often associated with poor prognosis." (PMID 22162712, 2011). "Authors have shown that high circulating levels of tumor necrosis factor α (TNFα) and other cytokines associated with tumor growth promoted low energy intake, increased energy expenditure and negative energy balance." (PMID 21941408, 2011). "In vitro studies have shown that co-culture of breast cancer cells and macrophages up-regulated MMP expression in macrophages in a TNF-α dependent fashion, causing enhanced invasiveness of the tumour cells." (PMID 22005011, 2011). "TNF can cause the differentiation of myeloid progenitor cells into endothelial cells in the tumor microenvironment." (PMID 24212934, 2011). "TNF-α is a circulating factor which causes necrosis of tumors when administered to tumor-bearing mice." (PMID 22013498, 2011). "In contrast, IFN-γ, TNF-α, IL-5, IL-4, IL-2 and low amounts of IL-10 were produced upon stimulation with the tumor cell lines encoding the HPV16E7wt and HPV16E7V constructs." (PMID 21892941, 2011). "The expression of TNFα in the tumour islets of patients with NSCLC is associated with improved survival suggesting a role in the host anti-tumour immunological response." (PMID 20573209, 2010). "The TNF-α also promotes tumour cell survival through the induction of genes encoding NF-κB-dependent antiapoptotic molecules." (PMID 20087353, 2010). "TNFα polymorphisms have been associated with susceptibility and outcome of various infectious, inflammatory and neoplastic diseases." (PMID 20396411, 2010). "The main analysis to assess the risk of developing an incident tumor under treatment with anti-TNFα agents was conducted as a nested case control study." (PMID 20064207, 2010). "Increasing evidences indicate that TNF-α acts as tumour-promoting factor and is linked to all steps of tumourigenesis including transformation, proliferation, angiogenesis, invasion and metastasis in many cancers." (PMID 20087353, 2010). "For example, the overexpression of TNFα in transgenic mice bearing a lung tumor is associated with an increase of the size of the tumor." (PMID 20339581, 2010). "Tumor promotion by 12-O-tetradecanoylphorbol-13-acetate (TPA) on the skin of TNF-α-deficient mice decreased compared to that in WT mice." (PMID 24281172, 2010). "Conversely, the presence of TNF-α on wild-type (WT) animals increased their susceptibility to tumour promotion." (PMID 20126546, 2010).
tumor (continued). "TNF-α was first described as an antiangiogenic compound causing tumor regression but also exhibits proangiogenic properties in some in vivo conditions." (PMID 20976179, 2010). "Selective AAVP homing, tumor-associated vascular expression of TNFα, systemic safety, and RECIST-based objective responses were observed (same species therapeutic index)." (PMID 19330034, 2009). "Tumour necrosis factor-alpha (TNF-α) was originally identified for its ability to induce apoptosis of tumour-associated endothelial cells and massive haemorrhagic necrosis of transplanted solid tumours." (PMID 19568235, 2009). "A number of antibodies have been developed to target pro-inflammatory cytokines, including TNF-α, IL-6 and IL-6 receptor, and these should be investigated for their potential to reverse tumour-associated impairment of drug metabolism." (PMID 19450285, 2009). "Histamine, as well as TNF-α, has been found to function synergistically with chemotherapeutic drugs in the treatment of tumors and they appear to primarily target the tumor-associated vasculature." (PMID 18257926, 2008). "Expression of TNF-α and Apaf-1 was significantly associated with tumor thickness, and osteopontin expression correlated with increased tumor cell proliferation (Ki-67)." (PMID 19061491, 2008). "Tumors have high levels of tumor necrosis factor-α(TNF-α), derived primarily from tumor-associated macrophages (TAMs)." (PMID 18779872, 2008). "Inducible nitric oxide synthase (iNOS) and nitric oxide (NO) are implicated in tumour pathology and, it is well known that TNFα induces iNOS and NO release." (PMID 18045456, 2007). "Understanding the mechanism(s) of TNF-α mediated growth arrest will be important in unraveling the contribution of tissue associated macrophages in tumor resistance." (PMID 17565690, 2007). "TNF-α mediates apoptotic or necrotic effects in many tumors depending on cell types, and causes growth inhibition in 40% of tumor cell lines." (PMID 17565690, 2007). "Tumour-associated macrophages cultured with M-CSF, TNF-α and IL-1α also showed formation of TRAP+ and VNR+ multinucleated cells." (PMID 16641914, 2006). "Contact coculture of Jurkats for 4 h with tumour cells either untreated or treated with TNF-α/IFN-γ caused a significant increase in caspase-3 activity compared to noncontact coculture (P<0.05)." (PMID 16929248, 2006). "It is secreted by lipopolysaccharide stimulated macrophages and causes necrosis of tumor in vivo when injected into tumor bearing mice and hence bearing the name tumor necrosis factor (TNF)." (PMID 17034639, 2006). "As previously reported in cachectic mice bearing the colon 26 tumour and in myotubes treated with TNF-α and interferon-γ, PIF induced selective loss of myosin, while actin levels remained unchanged." (PMID 15714207, 2005). "Our data support the notion that this indirect mechanism is the selective destructive effect of TNF-α on the tumour-associated vessels, thereby increasing vascular permeability." (PMID 12610519, 2003). "Tumour necrosis factor alpha (TNFα) has been implicated in the development and progression of tumours and is known to be important in angiogenesis and is a key proinflammatory cytokine." (PMID 12966432, 2003). "We have shown a significant association of both TNF+488A and TNF−859T with grade of tumour at presentation." (PMID 12966432, 2003). "The induction of tumour necrosis factor (TNF) by bacterial toxins was later shown to be the cause of haemorrhagic necrosis in tumours." (PMID 12799625, 2003). "As inhibition of NF-κB activation was clearly linked to increased apoptosis of various tumour cells, we decided to test NF-κB DNA binding activity in nuclear extracts from our cell lines incubated with TNF-α, a potent NF-κB stimulator." (PMID 12966434, 2003). "TNFα-deficient mice have a greatly reduced skin tumour growth and tumour induction in response to chemical carcinogens." (PMID 12966432, 2003).
tumor (continued). "Since the tumour-associated vasculature is the target of TNF-α, we expect that tumour microvessel density (MVD) is a predictor of the potentiating effect of TNF-α during isolated perfusions." (PMID 12610519, 2003). "At the present time, polymorphisms in the VEGF, MMP and PA system and TNF genes seem to be promising in the quest for markers influencing the severity and extent of tumour angiogenesis." (PMID 12402142, 2002). "The effects on angiogenesis and the presence of many functional polymorphisms in the TNF-α gene certainly warrant further study in neoplastic diseases." (PMID 12402142, 2002). "Whereas the cytotoxic drugs preferentially target tumour cells, TNF mainly affects the tumour associated vasculature, possibly resulting in destruction of the vessels and augmented accumulation of the drugs in the tumour tissue." (PMID 11953868, 2002). "Like FAA, DMXAA causes protracted inhibition of blood flow in murine tumours and induces extensive tumour haemorrhagic necrosis that is similar to that induced by TNF." (PMID 12177785, 2002). "This can be explained by an increase in IL-1 and TNF-α produced from monocytes recruited in the tumour site associated with a relative deficiency for both cytokines from the systemic circulation as a result of enhanced local consumption/degradation." (PMID 12085250, 2002). "Treatment with TNF-alpha (100 units ml-1) for 48 h enhanced the susceptibility of tumour cells to lysis by NK cells." (PMID 7908214, 1994). "In HCC, low expression of circPTPN12 is associated with poor prognosis and promotes tumor progression by activating the NF-κB pathway, which in turn enhances the secretion of immunosuppressive cytokines such as IL-6 and TNF-α, fostering an immune-resistant microenvironment." (PMID 41602547, 2026). "Similarly, CD4+ and CD8+ T cells producing IFN-γ and TNF-α were positively associated with improved tumor control, alongside mature NK cells producing IFN-γ, whose elevated presence further supported antitumor immunity." (PMID 41522339, 2026). "Endogenous TNF implements tumor cell necrosis activity, causing tumor‐related inflammation." (PMID 40968783, 2026). "Now, increasing evidence suggests that TNF-α pathway is one of the major mediators of cancer-associated inflammation and acts as a tumor-promoting factor, involved in all stages of tumor development, including transformation, proliferation, angiogenesis, invasion, and metastasis." (PMID 41188782, 2025). "Some postulate it could be part of a paraneoplastic syndrome or triggered by an alpha-tumor necrosis factor (TNF) release from a tumor or that there may be a genetic predisposition or infectious trigger." (PMID 40291223, 2025). "Additionally, the TNF signaling pathway plays a vital role as an inflammatory factor that promotes polarization and maintenance of tumor-associated macrophages." (PMID 40463876, 2025). "Conversely, vagotomy, which disrupts parasympathetic signaling, has been associated with increased tumor-associated macrophage (TAM) infiltration, elevated TNF-α levels, and accelerated tumor growth, ultimately reducing survival in a murine pancreatic cancer model." (PMID 40149585, 2025). "SYD has been found to reduce key inflammatory markers such as IL‐1, IL‐6, and TNF‐α, resulting in decreased tumor‐associated macrophage (TAM) infiltration and NF‐κB activation, thereby inhibiting Snail‐induced epithelial–mesenchymal transition (EMT) and subsequently CRC progression." (PMID 40119640, 2025). "Another key pro-inflammatory cytokine is TNF-α, which, through the activation of caspase pathways, causes cell death among the tumor cells but also induces the infiltration of immune cells at the site of the tumor, thus enhancing local antitumor immunity." (PMID 40309351, 2025). "Tumor necrosis factor-alpha (TNF-α) inhibition was initially hypothesized to increase cancer risk by impairing tumor immune surveillance." (PMID 41228267, 2025).
tumor (continued). "Consequently, tumor cells experiencing a loss of TNF-induced RIPK1 S25 phosphorylation exhibit increased RIPK1 activation and fail to recruit non-canonical IKK kinases (TBK1 and IKKε) to the TNFR1 complex." (PMID 41315176, 2025). "Similarly, the pathological role of TNF-α in driving inflammation-associated tumor progression has made it a rational candidate for combinatory interventions." (PMID 40430573, 2025). "The study concluded that a gene signature of TNF-α and tumor-associated macrophages could be a biomarker that effectively predicts bone invasion in these tumors." (PMID 40299639, 2025). "Serum ObR was also positively correlated with serum cytotoxic T lymphocyte-associated antigen 4 (CTLA-4), tumor necrosis factor α (TNF-α), programmed death protein-1 (PD-1), and programmed death ligand-1 (PD-L1), while showing an inverse correlation with ObR expression in tumor tissues." (PMID 41150099, 2025). "M1 macrophages are generally associated with pro-inflammatory and anti-tumor activities, capable of eliminating pathogens and inhibiting tumor growth by secreting inflammatory factors such as IL-12, tumor necrosis factor-alpha (TNF-α), and NO." (PMID 40055311, 2025). "TNF (tumor necrosis factor) encodes a multifunctional inflammatory cytokine originally identified for its ability to promote hemorrhagic necrosis of transplanted solid tumors and for its cytotoxic activity against tumor cell lines." (PMID 41197401, 2025). "Importantly, HPX was associated with a tumor-suppressive phenotype and increased apoptosis, consistent with TNF-α-mediated mitochondrial signaling, offering new insights into HCC pathogenesis and therapy." (PMID 41008813, 2025). "At the same time, Tumor-associated macrophage (TAMs) undergo a shift from an M2 anti-inflammatory phenotype to an M1 pro-inflammatory phenotype, accompanied by the release of inflammatory factors such as TNF-α, IL-1β, and IL-6." (PMID 40646377, 2025). "Commensal gastrointestinal (GI) microbes have been shown to prime tumor-associated innate immune cells to release pro-inflammatory cytokines such as tumor necrosis factor (TNF) and interleukin-12 (IL-12), thereby enhancing antitumor responses to chemotherapy and immunotherapy in preclinical models." (PMID 41375042, 2025). "The induction of TNF and genes implicated in T cell activation and proliferation together with a distinct modulation of immune-suppressive cues further corroborates the anti-tumor activity of BETi+SMACm combination exerted via the immune compartment." (PMID 40858106, 2025). "It must be, however, underlined that both IL-10 and TNFα may have both a pro- and an anti-tumor properties with respect to gastric carcinogenesis and that, therefore, our findings should be cautiously considered." (PMID 40534691, 2025). "In addition, the KEGG pathway enrichment demonstrated strong associations with key inflammatory and tumor-related pathways, including the TNF signaling, NF-kappa B, and IL-17 pathways." (PMID 40362530, 2025). "Furthermore, cuproptosis was negatively associated with the mitotic spindle, cell cycle, TGF-β, and TNF-α, indicating the important regulatory role of cuproptosis in tumor growth." (PMID 41142609, 2025). "While TNF-α is classically a pleiotropic cytokine implicated in inflammation and cancer progression, its elevated expression in this context likely reflects immune-mediated anti-tumor activity and apoptotic signaling." (PMID 41369848, 2025). "TNF-α could serve as a useful adjunct to traditional tumor markers, aiding in patient stratification and risk assessment." (PMID 40299527, 2025). "In addition, the pan-caspase inhibitor emricasan can inhibit the PANoptosis induced by co-treatment of IFN-γ and TNF-α and reduce cell death in DNA mismatch repair deficiency (dMMR) tumor." (PMID 40721869, 2025).